CD4 (CD4 molecule)
Diseases named in the same sentence as CD4 in open-access papers (continued):
Sharing a sentence is not in itself a finding about the gene and the disease.
malaria (continued). "Finally, in order to understand the influence of markers of HIV immunodeficiency and immune activation (HIV-1 VL, CD4+ counts and CRP) on malaria-specific antibodies, the concentrations of these markers were correlated with these antibody levels." (PMID 31470903, 2019). "Unlike, syphilis, malaria, HIV, and other POC diagnostic tests, CD4 count testing is aimed at improving the health outcomes of people living with HIV/AIDs by enabling the determination of clinical staging for the appropriate antiretroviral treatment." (PMID 31340833, 2019). "The patients' origin, the duration of the malaria therapy and the clinical course of the disease (uncomplicated and complicated) did also not correlate with the breadth of the CD4+ T cell response." (PMID 32038611, 2019). "We therefore compared the CD4+ T cell phenotypes of Ghanaian children with complicated malaria, uncomplicated malaria, asymptomatic Plasmodium falciparum (Pf) infection or no infection." (PMID 29555909, 2018). "Protective CD4 T cell phenotypes have not been precisely determined in malaria, or other persistent infections." (PMID 29630679, 2018). "Malaria patients and Plasmodium-infected rodents express OX40 predominantly on CD4+ T cells." (PMID 30631323, 2018). "We observed that overall, HIV and malaria co-infected patients had a significantly lower CD4 count (287.8 ± 12.2) compared to HIV positive without malaria (319.3 ± 8.6) (F = 4.438, df = 1, 757, p = 0.035, mean difference = -31.48)." (PMID 28346490, 2017). "This is probably not surprising since the effect of malaria parasitaemia is usually a short-term drop in CD4 count rather than long-term suppression." (PMID 28346490, 2017). "The findings from the study support the updated WHO guidelines that recommend continued use of CTX regardless of CD4 cell count where malaria is common." (PMID 28985732, 2017). "CD4 T cell help to CD8 T cells is needed to generate robust memory CD8 T cells, and the ability to generate fully functional TFH is critical for maintenance of effective long‐term humoral immunity against malaria." (PMID 28935714, 2017). "Considering the role of CD4 CTLs in controlling HIV, malaria, and other infections, it is intriguing to speculate about the activity of CD4 CTLs in tumor environment after TLR4 agonist adjuvant." (PMID 29029545, 2017). "With respect to CD4 T cells, recent observations in individuals vaccinated with RTS-S, a recombinant CSP-based vaccine, and in individuals naturally exposed to malaria suggest an important role for CD4 T cell production of TNF, with or without IFN-γ, as a potential immune correlate of protection." (PMID 28871201, 2017). "To determine whether such flexibility was altered during malaria we evaluated the expression of CXCR3 and CC chemokine receptor 6 (CCR6) by CD4+ T cell populations in P. vivax-infected patients BT and AT." (PMID 28700710, 2017). "Malaria was more common among patients with a CD4 count of <200/mm3 (p<0.001) neither on cotrimoxazole prophylaxis (p<0.001) nor on antiretroviral therapy (ART) (p<0.001)." (PMID 34532241, 2017). "Malaria was more frequently observed in severely immunosuppressed patients with a CD4 count < 200 (p<0.001), patients not on cotrimoxazole prophylaxis (p<0.001) and patients not on ART (p<0.001)." (PMID 34532241, 2017). "In utero exposure to malaria has been reported to induce numerous immunoregulatory mechanisms in the fetus, including expansion of FoxP3+ T regulatory cells, increased levels of suppressive cytokines such as IL-10 and TGF-β and diminished CD4 Th1 responses." (PMID 27717402, 2016). "Liposomal vaccine particles were engineered to display the malaria circumsporozoite (CSP) antigen on their surface, with helper CD4+ epitopes from distinct vaccine or viral antigens contained within the particle core, ensuring the B cell response is raised but focused against CSP." (PMID 27861512, 2016).
malaria (continued). "The difference in the CD4+ T cell counts between malaria coinfected patients and non-coinfected patients was observed to be significant statistically (p < 0.001)." (PMID 27619013, 2016). "Despite this, to our knowledge there remained no direct evidence that CD4+ T cells promoted B-cell responses during experimental malaria." (PMID 27812214, 2016). "Additionally, our data suggest that even in patients with higher CD4 counts and a longer duration on ART, CTX is still protective for malaria." (PMID 26731191, 2016). "Here, we explored the effect of Type I Interferon signalling via IFNAR1 on CD4+ T-cell and B-cell responses in two non-lethal murine models of malaria, P. chabaudi chabaudi AS (PcAS) and P. yoelii 17XNL (Py17XNL) infection." (PMID 27812214, 2016). "Adoptively transferred mature splenic CD4+ YFP+ GFP+ T cells were able to migrate to and accumulate within all examined organs of malaria parasite-infected mice, yet CD4+ YFP+ GFP+ T cells exhibited differences in their functional characteristics in the liver and lung from those in the spleen." (PMID 26459508, 2016). "Regardless, experiments using depletion both CD8+ and CD4+ T-cells during blood stage of P.chabaudi infections in mice resulted in a delayed clearance of the infection, suggesting a possible role for CD8+ T-cells during blood stage malaria." (PMID 27799922, 2016). "Taken together, our results suggest that HLA-A∗0201-restricted human CD8+ T cells almost solely mediate the protective anti-malaria immune response, with no contribution by humoral or CD4+ T-cell responses." (PMID 27502569, 2016). "However, that suppressive effect is limited to malaria-specific and polyclonal stimulation of PD1+CTLA4+CD4+ T cells." (PMID 27802341, 2016). "Although efficacy was low, subsequent development of CSP using a particle-based approach has led to the currently most advanced malaria sub-unit vaccine, RTS,S/AS01, that elicits 30 % protection in young children primarily mediated by anti-CSP antibodies and CD4+ T cells." (PMID 27448805, 2016). "Moreover, patients with recurrent malaria displayed decreased absolute counts and percentage of CD4+CD69+ and CD8+CD69+ as compared to primary malaria." (PMID 27581163, 2016). "Second, the effect of CD4 count at enrolment, CD4 count at ART initiation, and CD4 count during follow-up on malaria, was assessed within each trial arm; to examine whether the effect of CD4 count differed by CTX use." (PMID 27417903, 2016). "However, collecting capillary blood for CD4 counting is different than for instance for HIV diagnosis, malaria or glucose testing." (PMID 27556894, 2016). "In this study, a negative correlation was observed between malaria parasite density and CD4+ T cell count (p = 0.019)." (PMID 27619013, 2016). "Although malaria incidence was significantly lower in the CTX arm than on placebo, compared to participants on the lowest CD4 stratum, rate ratios were all close to 1 and P values were all above P = 0.30 for each of the three CD4 measures and within each arm." (PMID 27417903, 2016). "In contrast to what has been shown for B cells, memory CD4 T cells did not appear to undergo apoptosis during malaria, since absolute numbers of vaccine-induced, antigen-specific CD4 T cells were maintained at the peak of malaria parasite infection." (PMID 26366739, 2015). "Cotrimoxazole prophylaxis, recommended for adults and children living with HIV in Africa, for instance, has been reported to be effective in reducing clinical malaria, independent of baseline CD4." (PMID 26173396, 2015). "Additionally, the CD4+CD25hi+/CD4+CD25+ ratio was also examined and found to be significantly higher in malaria and eBL patients compared to the healthy controls (p = 0.004 and p = 0.014, respectively)." (PMID 28536409, 2015). "Direct antibody-mediated depletion of CD4+ T cells at the time of challenge does not impair anti-malaria immunity to the liver-stage, implying that at the effector level, CD8+ CTL are sufficient." (PMID 25426113, 2014).
malaria (continued). "Two children induced DBLα-tag specific IgG4 responses after the acute malaria episode but neither child had induced IL-4–secreting CD4+ T cells." (PMID 24453249, 2014). "Recent observations in individuals naturally exposed to malaria suggest an important role for CD4+ T cell production of TNFα, with or without IFNγ, as a potential immunologic correlate of protection." (PMID 24415936, 2014). "Considering that erythrocytes do not express HLA molecules and infected erythrocytes cannot be directly eliminated by CD4 and CD8 T cells in a HLA-restricted manner, antibodies and factors secreted by immune cells are thought to be responsible for clearance of malaria parasites from the blood." (PMID 25266106, 2014). "In the spleens, the augmentation in the numbers of CD4 and CD8 T cells may be explained by the clonal expansion observed in the course of malaria." (PMID 25329161, 2014). "In response, the mobile clinic was equipped with a point-of-care CD4 machine, a haemoglobinometer and rapid tests for HIV, malaria and syphilis, so that tests could be run on-site." (PMID 25378759, 2014). "Therefore, sorted splenic CD4+, CD8+ and DP-T cells from malaria-infected mice were intravenously transferred to EAE mice as soon as the clinical signs of EAE started to appear (around the 10th day after MOG35–55 immunization)." (PMID 25329161, 2014). "Although it has also been reported by other authors that malaria appears not to have any direct impact on the level of depletion of CD4+ T-lymphocytes in the HIV-infected subjects." (PMID 24729787, 2014). "Although this has not been explored in any detail in the context of malaria, the concept of Th plasticity opens new possibilities for studying the function and regulation of CD4+ T-cells in the control of Plasmodium infection and related immunopathology." (PMID 25628621, 2014). "We magnetically isolated CD4+ T cells that had been collected after the resolution of febrile malaria and found that they failed to produce IL-10 in response to iRBC stimulation in the absence of antigen-presenting cells." (PMID 24743880, 2014). "In RTS/S vaccine recipients, malaria-specific CD4+ T cells producing TNFα in the absence of IFNγ or IL-2 have recently been shown to correlate with protection from malaria infection." (PMID 24415936, 2014). "A detailed delineation on how CD4+ T-cells modulate the activation of effector cells such as CD8+ T-cells, macrophages, and B-cells in response to Plasmodium infection is critical to achieve the goal of generating protective treatments to control malaria." (PMID 25628621, 2014). "Two studies investigating imported P. falciparum malaria to non-endemic countries showed that severe malaria was more frequent in patients with a CD4 cell count <350/μl, (odds ratio 2.5 and 3.2)." (PMID 23941258, 2013). "We found that CPT in HIV-infected pregnant women with CD4 cell counts between 200 and 500 cells/μL does not have a statistically significant effect on malaria incidence during pregnancy (as compared to SP-IPTp), preterm birth, or low birth weight." (PMID 24363547, 2013). "Under natural exposure conditions, IFN-γ CD4+ T cell responses to P. falciparum appeared to be short-lived (half-life of 3.3 years) in areas of unstable malaria transmission, whereas IL-10 CD4+ T cells did not appear to decline for 6 years." (PMID 23967342, 2013). "Malaria, tuberculosis, pneumonia and herpes simplex virus have been associated with increased HIV VL and a more rapid decrease in CD4+T cell count among HIV-infected people not taking antiretroviral therapy (ART)." (PMID 23547778, 2013). "Plasma TNF-a, RANTES and antibodies to recombinant malarial proteins as well as levels of circulating CD4+ CD25high cells were comparable in malaria patients with or without filarial infections." (PMID 23837823, 2013).
malaria (continued). "Using a biologically-motivated mathematical model of sporozoite infection fitted to data from malaria-naive adults vaccinated with RTS,S and subjected to experimental P. falciparum challenge, we characterised the relationship between antibodies, CD4+ T cell responses and protection from infection." (PMID 23613845, 2013). "Herein, we have evaluated whether LCP constructs incorporating defined CD4+ and/or CD8+ T cell epitopes could induce epitope-specific T cell responses and protect against pathogen challenge in a rodent malaria model." (PMID 22936972, 2012). "Lastly, the mean CD4+ cell count was not significantly lower in malaria positive participants (245±195) when compared to malaria negative participants (301±211)." (PMID 22802967, 2012). "While the proportion of CD4+CD25high was higher in the Fulani ethnic group at the peak of malaria transmission season (p = 0.03), no clear pattern emerged for T regulatory cells expressing FoxP3+ and CD127low." (PMID 22283984, 2012). "In order to evaluate the effect of Tregs (i.e., CD25hi cells) on suppression of CD4+ T cell cytokine expression, equal aliquots of PBMC (n = 32 individuals) were mock-depleted or depleted of CD25hi cells and then stimulated with malaria or schistosoma antigen pools (n = 32)." (PMID 22348117, 2012). "The high level of CD4+ and CD8+ memory T cells may be due to frequent exposure to malaria parasites among the Thai population." (PMID 23049909, 2012). "Furthermore, there was a strongly significant synergistic interaction between CSP-specific IFNγ-IL2-TNF+ CD4+ T cells and anti-CSP antibodies in determining protection against clinical malaria (p = 0.002)." (PMID 23300801, 2012). "In this report, we have shown that memory CD8+ T cells developed in the absence of CD4 help failed to protect from live malaria challenge." (PMID 21245909, 2011). "The reduction in CD4 and CD8 triple positive MFT responses seen in malaria infected animals at 2 weeks after the P. yoelii infection was surprising because of the previously reported correlation between vaccine-induced triple-positive cells and protective immunity." (PMID 22205939, 2011). "Therefore, a profound comprehension of the mechanisms involved in CD4+ T cell activation and regulation during Plasmodium infection may improve the chances of developing effective vaccines and other potential immunotherapies to prevent severe malaria syndromes." (PMID 21814579, 2011). "The nature of memory T-cell populations elicited in malaria-naïve North Americans vaccinated with the 3D7 and FVO strains of MSP142 demonstrated induction of antigen-specific memory CD4 T-cells, however the contribution of CD8 T-cell memory subsets was not evaluated." (PMID 21935482, 2011). "The transfer of CD4+CD25+ cells harvested and sorted from EAE-malaria mice significantly diminished the evolution of clinical signs of EAE (p<0.01) as compared to animals that were immunized only, or even to the group that received CD4+CD25− cells." (PMID 21464982, 2011). "Conversely, we observed that none of the individuals exposed to malaria more than 4 years ago had detectable malaria-specific immediate IFN-γ+ CD4+ T cells." (PMID 21347351, 2011). "We concluded that conventional CD4+ T cells have a central role from the onset of P. chabaudi malaria, acting in parallel with non-conventional CD4+ T cells as a link between innate and acquired immunity." (PMID 21814579, 2011). "Memory CD8+ T cells induced by irradiated malaria sporozoites are critical for elimination of liver stage parasites and the optimal development of primary effector CD8+ T cells to sporozoite antigen is dependent on the presence of CD4+ helper T cells." (PMID 21245909, 2011). "Some reports indicate that expansion of CD4+CD25+Foxp3+ during murine malaria did not prevent murine CM." (PMID 21439091, 2011).
malaria (continued). "Despite the eventual higher antibody titers in mice receiving chronically stimulated CD4+ T cells, it is unlikely that antibody was the mechanism of parasite control, as at this early stage of infection anti-malaria antibodies were not detectable." (PMID 21124875, 2010). "The SIV-infected animals had characteristic peripheral CD4+ T cell depletion, but this decline was more than twice as rapid in the co-infected group than in the SIV-only group (regression analysis: slope for SIV/malaria = −3.30, SIV-only = −1.35; p = 0.028)." (PMID 19774084, 2009). "Case-patients were more likely to have a CD4 count <350/μL than were asymptomatic controls (OR 23.00, 95% CI 3.35–158.00, p<0.0001) but not controls with uncomplicated malaria (OR 3.00, 95% CI 0.83–10.83, p = 0.32)." (PMID 19402961, 2009). "CM CD4+ T cells and CCR5+ memory CD4+ T cells proliferatively responded to parasitemia, presumably developing the adaptive immune response against the malaria parasite." (PMID 19774084, 2009). "All SIV-infected animals had a decline in CD4+/CD8+ T cell ratios, but this decline was nearly twice as rapid in the co-infected group than in the SIV-only group (regression analysis: SIV/malaria = −0.0029." (PMID 19774084, 2009). "Moreover, we have identified a population of FOXP3−, CD45RO+, CD4+ T cells which co-produce IL-10 and IFN-γ and which are more prevalent in children with uncomplicated malaria than in those with severe disease." (PMID 19343213, 2009). "A study conducted at the Malawi study site found that HIV positive adults with CD4 cell counts <200 cells/mm3 had a higher incidence of malaria than those with counts >500 cells/mm3 though the prevalence of malaria was not influenced by CD4 count." (PMID 18320064, 2008). "Protection against clinical malaria depends on cellular immunity, which may be impaired in HIV-infected children with low CD4 lymphocyte counts." (PMID 17973997, 2007). "CD4+ T cells have been demonstrated to play a central role in the immune control of Plasmodium infection, where IFN-γ- and TNF-α-producing Th1 cells are critical for controlling blood-stage malaria, while Treg cell-mediated immunomodulatory responses help limit immune-mediated host damage." (PMID 41422632, 2025). "Likewise, the AS01 adjuvant system—comprising MPL, QS-21, and liposomes—has been widely validated in malaria, RSV, and herpes zoster vaccines and is known to promote robust germinal center responses, CD4+ T cell polyfunctionality, and CD8+ T cell cross-presentation." (PMID 41295535, 2025). "Thus, in summary, we have discovered that cMaf is critical in experimental malaria for the early differentiation of Tfh cells, while Myo1f and Prr13 play no role in the biology of Plasmodium-specific CD4+ T cells during blood-stage infection." (PMID 40132035, 2025). "Observational studies suggest both clinical malaria and asymptomatic Pf parasitemia may be more frequent or more severe in persons living with HIV, with higher levels of parasitemia and correlated with lower CD4 counts." (PMID 38194272, 2024). "CD4+-T cells were higher in malaria-infected children, both in HIV positive and negative (p=0.049)." (PMID 36600836, 2023). "IFN-γ is produced by both CD4 + and CD8 + T cells and other immune cells such that the early appearance of IFN-γ after infection correlate with rapid parasite clearance thereby conferring some protection against the development of clinical malaria symptoms in humans and in mice." (PMID 37060041, 2023). "The elevated proportion of CD4+CCR5+ T cells induced by Plasmodium parasites might provide more target cells for SIV replication and account for the higher viral load in the pre-existing malaria group than in the subsequent malaria group." (PMID 35778766, 2022).